CLDN25 (claudin 25)
Description:
Plays a major role in tight junction-specific obliteration of the intercellular space, through calcium-independent cell-adhesion activity.
Tractability: Antibody: UniProt places it where antibodies can reach, with high confidence; UniProt predicts a signal peptide or a membrane-spanning region; its Gene Ontology location is reachable by antibodies, with medium confidence.
Gene: Protein-coding gene on chromosome 11 (113,779,796 to 113,780,485, forward strand). Ensembl gene ENSG00000228607.
Subcellular location: Cell junction, tight junction; Cell membrane
Gene Ontology:
Molecular function: structural molecule activity
Cellular component: tight junction; bicellular tight junction; plasma membrane; apical plasma membrane; membrane
Genetic constraint (gnomAD): Loss-of-function variants: 0 observed, 0.0766 expected, observed/expected ratio (o/e) 0, 90% interval 0 to 1.89. That is too few expected variants to judge how well the gene tolerates losing a copy. Missense variants: 286 observed, 294.68 expected, observed/expected ratio (o/e) 0.97, 90% interval 0.88 to 1.07. Synonymous variants: 117 observed, 119.82 expected, observed/expected ratio (o/e) 0.98, 90% interval 0.84 to 1.14.
Homologues: Orthologues: chimpanzee CLDN25 (99% identical), macaque CLDN25 (89% identical), dog CLDN25 (82% identical), rabbit CLDN25 (79% identical), mouse Cldn25 (78% identical), rat Cldn25 (76% identical), pig CLDN25 (76% identical). Paralogues in human: CLDN22 (47% identical), CLDN24 (47% identical), CLDN6 (31% identical), CLDN9 (31% identical), CLDN14 (29% identical), CLDN7 (29% identical), CLDN1 (29% identical), CLDN17 (29% identical), CLDN19 (29% identical), CLDN3 (28% identical), CLDN4 (28% identical), CLDN5 (26% identical), and 10 more.
Diseases named in the same sentence as CLDN25 in open-access papers:
CLDN25 is named in the same sentence as 1 disease in open-access papers, as found by Europe PMC text mining. Sharing a sentence is not in itself a finding about the gene and the disease. The quoted sentences say what the papers report.
leukodystrophy (1 paper, 2024). Leukodystrophies are a group of rare, progressive, metabolic, genetic diseases that affect the brain, spinal cord and often the peripheral nerves. "While it remains unclear how this de novo CLDN-25 mutant induces leukodystrophy, our findings strongly suggest that this mutation induces haploinsufficiency of CLDN-25." (PMID 38493358, 2024).